RN7SL369P (RNA, 7SL, cytoplasmic 369, pseudogene)
Gene: Miscellaneous RNA gene on chromosome 14 (67,705,954 to 67,706,252, forward strand). Ensembl gene ENSG00000241542.
Homologues: Orthologues: chimpanzee Metazoa_SRP (99% identical), macaque Metazoa_SRP (92% identical). Paralogues in human: RN7SL2 (80% identical), RN7SL1 (80% identical), RN7SL45P (79% identical), RN7SL3 (78% identical), RN7SL357P (78% identical), RN7SL126P (77% identical), RN7SL492P (77% identical), RN7SL615P (77% identical), RN7SL174P (77% identical), RN7SL326P (77% identical), RN7SL408P (77% identical), RN7SL451P (77% identical), and 703 more.